RNU7-137P (RNA, U7 small nuclear 137 pseudogene)
Gene: Small nuclear RNA gene on chromosome 20 (18,095,571 to 18,095,632, reverse strand). Ensembl gene ENSG00000252597.
Homologues: Orthologues: macaque U7 (90% identical), pig U7 (79% identical). Paralogues in human: RNU7-67P (85% identical), RNU7-10P (84% identical), RNU7-167P (84% identical), RNU7-35P (84% identical), RNU7-7P (84% identical), RNU7-175P (82% identical), RNU7-52P (82% identical), RNU7-57P (82% identical), RNU7-60P (82% identical), U7 (82% identical), RNU7-105P (81% identical), RNU7-113P (81% identical), and 141 more.